IGF1 (insulin like growth factor 1)
Diseases named in the same sentence as IGF1 in open-access papers (continued):
Sharing a sentence is not in itself a finding about the gene and the disease.
myopia (continued). "We found that the SNP rs2162679 in IGF1 was significantly associated with myopia in this young Chinese population, which provided clues for in-depth mechanism interpretation that IGF-1 may play a regulating role in the progression of myopia shift." (PMID 32025377, 2020). "It reminded us that IGF-1 might play similar roles in myopia and cancer." (PMID 32025377, 2020). "Even if IGF-1 is involved in cellular growth and differentiation as well as in the apoptosis, IGF-1 gene may not determine the susceptibility to high or very high myopia in Caucasians and Chinese." (PMID 31781378, 2019). "We found that none of the individual studies significantly affected the pooled ORs by excluding each study in turn in every comparison, and the association between IGF-1 rs12423791 and high myopia did not change in any genetic models, suggesting the high stability of the meta-analysis." (PMID 26076017, 2015). "Growth factors like IGF1 and FGF2 regulate ocular growth, contributing to myopia, and TGF-β family members are important for early eye development and myopia pathogenesis." (PMID 40110040, 2025). "The study explored the association between the SNPs (rs5742632, rs10860860, rs17576, and rs2236416) of IGF-1 and MMP-9 and high myopia in a Han population." (PMID 35647299, 2022). "Although intravitreal insulin and insulin-like growth factor-1 (IGF-1) can induce myopia in chicks, it is not known if both or only one of the two signaling pathways is responsible for this effect." (PMID 23112573, 2012). "Since elevated DBP would increase insulin tolerance and decrease insulin-like growth factor-1 (IGF-1) production and it was demonstrated that IGF-1 could increase myopia, a clear link between DBP and myopia can be appreciated." (PMID 18334949, 2008). "Therefore, in view of the fact that myopia is a polygenetic disease, IGF-1 would not play independently important roles in the development of high myopia." (PMID 26076017, 2015). "Therefore, it is possible that IGF-1 has an effect on the development of myopia in birds but not in humans." (PMID 23734076, 2013).
vitamin D deficiency (40 papers, 2010 to 2025). A nutritional condition produced by a deficiency of VITAMIN D in the diet, insufficient production of vitamin D in the skin, inadequate absorption of vitamin D from the diet, or abnormal conversion of vitamin D to its bioactive metabolites. "Transfusion-dependent thalassemia (TDT) significantly impacts a child’s growth, potentially causing stunting, an increased risk of vitamin D deficiency, and reduced insulin-like growth factor-1 (IGF-1) levels." (PMID 39594890, 2024). "Nonetheless, muscle-liver crosstalk is influenced by numerous other factors, such as vitamin D deficiency, hormonal changes (GH; IGF-1; testosterone levels), low physical activity, aging, and diet composition." (PMID 35111794, 2021). "Specifically, we propose that muscle atrophy linked with serum vitamin D deficiency is associated with a reduction of IGF-1 and deactivation and activation of Akt and FOXO3." (PMID 31281588, 2019). "Specifically, certain types of ART have been linked to lipodystrophy, vitamin D deficiency, and reduced serum IGF1 levels." (PMID 25890304, 2015). "Patients with vitamin D deficiency appear to have lower levels of IGF-1, and this may partly explain the alterations of the growth plate in children with rickets." (PMID 30885216, 2019). "In adult CKD, anorexia and reduced physical activity together with the accumulation of pro-inflammatory cytokines, metabolic acidosis, and vitamin D deficiency and insulin-like growth factor-1 (IGF-1) signaling derangement, may contribute to the development of frailty." (PMID 37610434, 2023). "Other key factors that may significantly impact the muscle-liver crosstalk are vitamin D deficiency, unhealthy/diet composition, oxidative stress, aging, physical inactivity, and several hormonal changes [growth hormone (GH), insulin-like growth factor 1 (IGF-1), testosterone and osteocalcin]." (PMID 35111794, 2021). "Therefore, we assume that vitamin D deficiency might be associated with downregulated IGF-1 in the atrophied skeletal muscle." (PMID 31281588, 2019). "It has been suggested that the supplementation of vitamin D to the diet of humans with vitamin D deficiency served as a link between the proliferating cartilage cells of the growth plate and GH/IGF-1 secretion and the increase in IGF-1 and 25(OH)D3 levels." (PMID 34727644, 2022). "Vitamin D deficiency decreases protein synthesis (through a signaling cascade: decreased IGF-1/Akt/mTOR), and on the other hand, decreased IGF-1/Akt activates FoXO and triggers muscle atrophy by elevation of MuRF1 and atrogin-1." (PMID 35955530, 2022). "We found two main areas of interest: the vitamin D deficiency status in patients affected by GH deficit (GHD) and the relationship between serum vitamin D metabolites and IGF-1." (PMID 30885216, 2019). "Vitamin D deficiency might activate the renin-angiotensin system, increase serum level of parathyroid hormone (PTH), and decrease insulin-like growth factor 1 (IGF-1) level." (PMID 25822845, 2015). "This study aimed to investigate the prevalence of vitamin D deficiency in patients with CRA compared with controls and to explore the correlations between the serum levels of vitamin D metabolites (cholecalciferol, calcidiol, and calcitriol) and the IGF axis (IGF-1 and IGFBP-3)." (PMID 39200386, 2024).
bladder cancer (39 papers, 2013 to 2025). "Urothelial overexpression of IGF1 increases susceptibility to p-cresidine-induced mouse bladder cancer, especially transitional cell carcinoma." (PMID 32733809, 2020). "IGF1 can block apoptosis in human bladder cancer cells and increase circulating IGF1, thereby augmenting risk of BLCA patients." (PMID 32884943, 2020). "Studies have suggested that MetS status was associated with elevated levels of inflammatory factors, reactive oxygen, and serum insulin-like growth factor 1 (IGF-1), which might provide a protumorigenic environment and are risk factors for bladder cancer." (PMID 36263231, 2022). "Furthermore, patients with bladder cancer had higher plasma levels of IGF-1, which were associated with an increased risk of bladder cancer." (PMID 32733809, 2020). "However, the role of plasma IGF1 in assessing bladder cancer risk remains controversial." (PMID 32675942, 2020). "For further validation, Kaplan–Meier survival plots with GHR, GH1, IGF-1 receptor (IGF1R), or IGF1 as the reference gene were generated from TCGA database, including 405 patients with bladder cancer." (PMID 40806252, 2025). "For example it was shown that restoring the levels of IGF1 reverses the protective effects of CR in a model of bladder cancer." (PMID 37686596, 2023). "In bladder cancers, stromal CAFs enhanced cisplatin resistance via stimulating IGF-1/ERbeta/Bcl-2 signaling, wherein CAFs regulated ERbeta expression through IGF-1/AKT/c-Jun signaling following c-Jun phosphorylation and promoted ESR2 gene transcription." (PMID 35326670, 2022). "A study reported that plasma IGF1 is highly expressed in patients with bladder cancer; measuring plasma IGF1 values can help assess bladder cancer risk." (PMID 33888644, 2021). "Bladder cancer cells overexpress insulin-like growth factor 1 (IGF-1) and a case-control study in humans showed that patients with bladder cancer have higher level of IGF-1 and lower levels of IGF binding protein-3 than their controls." (PMID 24466131, 2014). "In a US case-control study, patients with bladder cancer have higher plasma levels of IGF-1 and lower levels of IGFBP-3 than controls." (PMID 23437204, 2013). "Similarly, CAF derived IGF-1 promotes cisplatin resistance in bladder cancer as well as the tyrosine kinase inhibitor gefitinib in non-small cell lung cancer (NSCLC)." (PMID 39165364, 2024). "Molecular pathways like PI3K/AKT/mTOR, activated in obese patients due to high circulating levels of IGF1, could be a potential therapeutic target in bladder cancer patients with high BMI." (PMID 39723162, 2024). "The high expression of ABCB9, SPTBN2, GULP1, IGF1, P4HB, NES and DPYSL2 and the low expression of ANXA6, OAS1, RAD9a, DNASE2B and FANCF would be beneficial to the prognosis of bladder cancer patients." (PMID 37845668, 2023). "Paracrine interaction between bladder cancer cells and CAFs stimulates synthesis of IGF-1 by tumor cells, upregulating ERβ via an activated IGF-1/IGF-R/AKT/c-Jun signaling axis resulting in an increase in Bcl-2." (PMID 35267539, 2022). "On the contrary, decorin enhances IGF1-evoked IRS-1 degradation and inhibits Akt and MAPK activation, thus blunting the ability of the IGF1R to promote ligand-evoked bladder cancer cells migration and invasion." (PMID 33673232, 2021). "As shown in bladder cancer cells, decorin binds with similar affinities both the IGF1R and IGF1 at distinct sites and inhibits IGF1-mediated IGF1R phosphorylation, without affecting IGF1R protein levels." (PMID 33673232, 2021). "Together, this study identified four prognostic hub immune-related genes, including MMP9, IGF1, CXCL12 and PGF, which might play a vital role in bladder cancer development." (PMID 32675942, 2020).
cervical cancer (39 papers, 2007 to 2025). A primary or metastatic malignant neoplasm involving the cervix. "The association between these polymorphisms, tissue and blood serum levels of IGF-1, and cervical cancer risk and progression is evaluated." (PMID 25384883, 2015). "Yet again, it is unclear why increased levels of IGF-1 would have a protective effect on the risk of cervical cancer precursors and that the protection would be stronger among younger women." (PMID 25333772, 2014). "As to cervical cancer, studies showed lower serum IGF-1 level correlated to increased risk of cervical cancer and its precancer lesions." (PMID 18781172, 2008). "This study aims to investigate the association of IGF-1 system and clinical outcome of cervical cancer, by analysing the serum levels of IGF-1 and IGFBP-3, and tissue abundances of IGF-1R for the same patient." (PMID 18781172, 2008). "In this work, we evaluated the consequences of increased O-GlcNAcylation on IGF-1 effects in cervical-cancer-derived CaSki cells." (PMID 35296731, 2022). "Another study stresses the critical role of KCC4 in the malignant behaviors of cervical cancer cells, especially IGF-1 and epidermal growth factor (EGF) dependent cancer cell invasiveness." (PMID 35008759, 2021). "In conclusion, miR-186-3p inhibits tumorigenesis of cervical cancer by repressing IGF1, which inactivates the PI3K/Akt signaling pathway, implicating miR-186-3p as a potential new target for the treatment of cervical cancer." (PMID 34551673, 2021). "The expressions of KCCs and its potent stimulator IGF-1 are abundant in cervical cancer tissues but are nearly undetected in the adjacent normal cervical epithelial and non-cancerous stromal tissues." (PMID 35008759, 2021). "Overexpression of KCC2 in cervical cancer cells enhanced IGF-1-stimulated cell migration and invasiveness." (PMID 35008759, 2021). "A retrospective analysis of patients with cervical cancer showed that IGF1/IGF1R signaling is involved in tumor formation and clinical outcome." (PMID 34071893, 2021). "A further study established the critical role of K+-Cl− cotransport in IGF-1 signaling to promote the growth and spread of cervical cancers." (PMID 35008759, 2021). "Consistent with this, Insulin-like growth factor 1(IGF1R) is reported to promote cervical cancer development." (PMID 32655987, 2020). "By contrast, results from the Biomarkers of Cervical Cancer Risk study of 329 cases and 621 controls suggest that elevated levels of IGF-1 among younger women show a protective and shielding effect in the precursors of cervical cancer." (PMID 33291721, 2020). "The authors of the study concluded that more candidates should be enrolled in further studies to realize the differences in serum levels of IGF-1 between normal individuals, patients with precancer lesions and cervical cancer." (PMID 25333772, 2014). "It has been observed that the growth and invasiveness of cervical cancer cells are dose-dependently stimulated by IGF-1, whereas the growth and invasiveness of normal cervical epithelial cells are not." (PMID 25333772, 2014). "Diverse growth factors, such as EGF, transforming growth factor β (TGF-β) and insulin-like growth factor 1 (IGF-1) have been shown to induce EMT and are significantly associated with the invasiveness, metastasis and recurrence of cervical cancer." (PMID 23936413, 2013). "Little information is available on the clinical implication of IGF-1 system in cervical cancer except for a small clinical study showing higher serum level of IGF-1 in women with squamous intraepithelial lesion than normal control." (PMID 18781172, 2008). "This study was aimed to identify the expression and the correlation of insulin-like growth factor-1 (IGF-1) system and their prognostic impacts in cervical cancer." (PMID 18781172, 2008). "More candidates should be enroled in further studies to realise the differences of serum levels of IGF-1 between normal individuals, patients with precancer lesions and cervical cancer." (PMID 18781172, 2008).
cervical cancer (continued). "We provide evidence that IGF-1 system has a certain function in tumour formation and clinical outcome of cervical cancer." (PMID 18781172, 2008). "The results suggest the important function of IGF-1 system in predicting the clinical outcome of patients with early-stage cervical cancer." (PMID 18781172, 2008). "IGF-1 is related to lymphangiogenesis, and Chen found that LncCCLM could reduce lymphangiogenesis and lymphatic metastasis in cervical cancer by accelerating the degradation of IGF-1 mRNA." (PMID 36105188, 2022). "Knockdown of IGF1 reversed the results of miR-186-3p inhibitor in cervical cancer cells." (PMID 34551673, 2021). "How insulin-like growth factor 1(IGF1) and miR-186-3p contribute to the development of cervical cancer (CC) remains unclear." (PMID 34253194, 2021). "The study of Lu X showed that miRNA-186-3p could inhibit the proliferation and migration of cervical cancer cell lines by inhibiting the expression of IGF1, and induce the apoptosis rate of cervical cancer cells." (PMID 34911543, 2021). "In cervical cancer tissues and cells, miR-186-3p was downregulated, and IGF1 was upregulated." (PMID 34551673, 2021). "Studies provided evidence that targeting IGF1 by miR-186-3p can regulate cervical cancer progression, and miR-125 inhibited cervical cancer progression and development by inhibiting VEGF and PI3K/AKT signaling pathway, providing more insights into the treatment of cervical cancer." (PMID 34530829, 2021). "In the future, the association of IGF-1, the IGF system and the 19-19 repeat P1 promoter IGF-1 gene and the clinical outcome of cervical cancer patients in post-treatment samples may add significance in disease mapping as a prognostic marker." (PMID 25384883, 2015). "(iii) The colocalisation of IGF-1 and IGF-1R in the cancerous tissues, and the lack of correlation between circulating IGF-1 or IGFBP-3, and IGF-1R overexpression in cervical cancer cells suggest likely autocrine or paracrine IGF-1 stimulation of IGF-1R signalling." (PMID 18781172, 2008). "In early-stage cervical cancer, IGF-1 system may have a paracrine or autocrine function and the adverse impacts on prognosis by IGF-1R overexpression are implicated." (PMID 18781172, 2008). "Thus, blockade of KCC4 trafficking and surface expression may provide a potential target for preventing IGF-1- or EGF-dependent cervical cancer metastasis." (PMID 35008759, 2021). "Endometrial CSCs are supported by pathways involving TGFβ, BMP2, and Netrin-4/c-Myc signaling, while in cervical cancer, VEGF, IGF-1, Gremlin-1, and TGFβ-mediated circuits enhance stem-like phenotypes and drug resistance." (PMID 41373619, 2025). "Specifically, the genes ABL1, BAX, FASN, and PLAU exhibited abnormally high expression levels in cervical cancer specimens, in stark contrast to BCL2, IGF1, and NTRK3, which were markedly under-expressed." (PMID 38988712, 2024). "We analyzed the effects of miR-186-3p and insulin-like growth factor 1 (IGF1) on the proliferation, invasion, and apoptosis of cervical cancer cells in vitro by regulating the PI3K/Akt signaling pathway." (PMID 34551673, 2021). "Insulin receptor and insulin-like growth factor 1 (IGF-1) are expressed in most cancer cells, and IGF-1 can stimulate invasion and proliferation of cervical cancer cells." (PMID 25963193, 2015). "DNA from the blood and tissue of study patients was isolated and the correlation between the CA repeats situated in the P1 promoter region of the IGF-1 gene, serum and tissue level of IGF-1 and cervical cancer development was investigated." (PMID 25384883, 2015). "It was pointed out that IGF-1, acting through IGF-1R, interacted with αvβ3 integrin in cervical cancer cell invasiveness and proliferation." (PMID 25333772, 2014). "We have pointed out that IGF-1, as a stimulator through IGF-1R signalling, interacted with αvβ3 integrin in cervical cancer cell invasiveness and proliferation." (PMID 18781172, 2008).